IDO1 (indoleamine 2,3-dioxygenase 1)
Diseases named in the same sentence as IDO1 in open-access papers (continued):
Sharing a sentence is not in itself a finding about the gene and the disease.
gastric cancer (39 papers, 2013 to 2025). A primary or metastatic malignant neoplasm involving the stomach. "In multiple previous studies, IDO1 expression has been associated with poor patient outcomes in not only gastric cancer, but also lung, prostate, esophagus, and uterine malignancies." (PMID 36421674, 2022). "As an exploratory analysis, we conducted non-parametric Spearman rank correlation tests to assess the associations of PD1/PD-L1 and IDO1 expression in gastric cancers." (PMID 35203450, 2022). "Analogously, another research found that both WARS and indoleamine 2,3-dioxygenase 1 (IDO1) were highly expressed in Epstein-Barr virus-associated and microsatellite instability-high subtypes of gastric cancer." (PMID 33330488, 2020). "qPCR revealed that GPX4 knockdown in gastric cancer cells led to a corresponding decrease in IDO1 mRNA levels." (PMID 40365295, 2025). "We identified 12 driver genes potentially involved in the gastritis-to-cancer transformation, with CHI3L1, MMP12, CXCL6, IDO1, and CCL20 emerging as the top five genes via a early gastric cancer diagnostic model." (PMID 40108688, 2025). "Exosomes-derived T-cell co-stimulator and indoleamine 2,3-dioxygenase 1 levels in peripheral blood can predict the occurrence of immune-related adverse events in gastric cancer patients undergoing immunotherapy." (PMID 40708696, 2025). "The PCR results showed that in contrast to normal cells, IDO1 was poorly expressed in gastric cancer cells MKN-45, AGS, and MGC-803 by PCR." (PMID 38539263, 2024). "We also analysed a possible link between the immune checkpoint PD1/ PDL1, IDO1 and AhR expression in gastric cancers." (PMID 35203450, 2022). "Recently, high IDO1 expression and l-Kyn presence were confirmed to promote both gastric cancer cell growth and migration ability by increasing extracellular matrix expression, especially the COL12A1 gene." (PMID 34203517, 2021). "IDO1 (Indoleamine 2,3-dioxygenase 1) inhibits host anti-tumor immune response by exhausting tryptophan in tumor microenvironment, but the pathogenic mechanisms of IDO1 in gastric cancer (GC) cells need to be further explored." (PMID 31315643, 2019). "To further explore the link between EBV and IDO1, we analyzed a separate cohort of Vietnamese gastric carcinoma samples by real time RT-PCR." (PMID 23671415, 2013). "The analysis of IDO1 levels for each of the 32 gastric carcinomas showed that the samples with the highest number of EBV reads had the highest levels of IDO1 expression." (PMID 23671415, 2013). "Additionally, in CRC and gastric cancer, TAMs have been shown to upregulate IDO1, which converts tryptophan into kynurenine, a key immunosuppressive metabolite that dampens T-cell activation and promotes immune evasion." (PMID 40361394, 2025). "Moreover, analysis of the TCGA gastric cancer database (n = 375) showed that expression of IFNG was positively correlated with IDO1 expression in GC." (PMID 38994917, 2024). "Also, MAPK signals activated the IDO1 level via the kynurenine/AhR perturbation loop pathway in gastric cancer." (PMID 35687267, 2023). "IDO-1 plays a crucial role in tumor metastasis in many cancer types, such as gastric cancer, and the increased expression of IDO-1 and expression of the core gene COL12A1 synergistically improve cancer cell invasion and metastasis via the MAPK transduction pathway." (PMID 34367975, 2021). "Even though the molecular mechanisms underlying type XII in gastric cancer have not been fully elucidated, some studies suggest that IDO1 and type XII collagen together could induce gastric metastasis." (PMID 39048763, 2024). "Expression of IDO1, CD155, and ADAM17 is also associated with poor survival, including gastric cancer (GC)." (PMID 34943606, 2021). "Knocking down both IDO1 and COL12A1 in gastric cancer cells (SGC-7901) led to greater ERK phosphorylation inhibition and reduced cell migration." (PMID 39048763, 2024).
gastric cancer (continued). "We found that IDO1 expression was upregulated in ER-HER2 and HER2 + breast, colon, and endometrial cancers, thyroid cancer, gastric cancer, and gynecological tumors." (PMID 38539263, 2024). "For example, IDO1 and COL12A1, which were found to synergistically promote gastric cancer metastasis, appear to be promising targets for the treatment of gastric cancer." (PMID 34968391, 2021). "Furthermore, TRIM28 has been found to facilitate gastric cancer cell proliferation by the serum response factor/Indoleamine 2,3-dioxygenase (SRF/IDO1) axis, whereby it regulates IDO1 expression by modulating SRF levels." (PMID 39768197, 2024). "In this context, IDO1 and type XII collagen might be promising targets to treat gastric cancer, and PRO-C12 could help to assess which patients respond to treatment." (PMID 39048763, 2024). "The interaction of two molecules was also observed on tissue-derived transcript levels extracted from gastric cancer datasets TCGA and GSE62254, suggesting that ICOS and IDO1 may exert analogous functions in modulating tumor immune microenvironment (TIME)." (PMID 36077704, 2022). "We propose that stratification of gastric carcinomas into EBV-negative, EBV-low and EBV-high may provide indicator value for the use of IDO1 inhibitors as adjuvant therapies against hiEBVaGCs." (PMID 23671415, 2013). "In addition, CM derived from two gastric cancer cell lines did not induce KYNU or IDO‐1 in NFs, while PAPP‐A was slightly upregulated by CM from one of the two cell lines." (PMID 34379869, 2022). "Therefore, since we observed a higher expression of IDO1 and TDO2 in gastric cancers as compared to non-tumoral tissue, we further analyzed AhR expression and protein localization in gastric tumors." (PMID 35203450, 2022). "In this study, we found that EBV+ gastric cancer, HPV+ cervical and head-neck squamous cell cancer, and HCV+ liver cancer (but not HBV+ liver cancer) showed over-expression of IDO-1, but only EBV+ gastric cancer and HPV+ head and neck squamous cell cancer showed over-expression of IDO-2." (PMID 34367262, 2021).
endometrial cancer (35 papers, 2009 to 2025). Primary or metastatic malignant neoplasm involving the endometrium (mucous membrane that lines the endometrial cavity). "We focus especially on the selected aspects that contribute to endometrial cancer biology, such as IDO1 activity (expressed as l-Kyn level) and RAGE implicated with inflammatory and metabolic status." (PMID 33922995, 2021). "IDO1 is involved in immune regulation and in endometrial cancer it is often associated with the check point protein PD-L1 as determined by IHC staining." (PMID 33922995, 2021). "Together, it makes this model suitable for identification and testing novel immunotherapeutics for HER2- and IDO1-associated pathology shown to be important in endometrial cancer or endometriosis." (PMID 33922995, 2021). "IDO1 contributes to the immunosuppression of the tumor microenvironment, and elevated levels of IDO1 have been correlated to shorter survival in ovarian and endometrial cancers, as well as UC." (PMID 39054491, 2024). "The impact of IAA on cytokine production and indoleamine-2,3-dioxygenase 1 (IDO1) expression in an endometrial cancer (EC) cell line, as well as their effect on Treg and Teff cells, and M1 and M2 macrophage populations were examined in EC patients and tumor-grafted mice." (PMID 38540186, 2024). "Our study sheds light on the link between IDO1 induction and uterine Peptostreptococcus dysbiosis and provides a potential rationale for the role of Peptostreptococcus species in immune tolerance induction in type I endometrial cancer." (PMID 38540186, 2024). "Multiple lines of evidence link IDO1 expression with poor prognosis in patients, including those diagnosed with acute myeloid leukemia, non-small cell lung cancer, colorectal cancer, prostate cancer, endometrial cancer, ovarian cancer, and EC." (PMID 37903782, 2023). "The IDO1 gene is high expressed in manly tumor cells included endometrial cancer." (PMID 37671947, 2023). "Current development status of IDO1 inhibitor strategies in advanced endometrial cancer." (PMID 36119020, 2022). "On the other hand, the IDO1 inhibitor methyl-DL-tryptophan has increased the efficacy of paclitaxel in endometrial cancer xenografts, suggesting that the inhibition of IDO1 may improve the chemosensitivity." (PMID 25955018, 2015). "It should be noted that baseline Kyn levels in our patient cohort were higher than those measured in healthy controls (median Kyn concentration = 1.86 μM; number of samples = 20), probably reflecting the expression of functional IDO1 by the ovarian and endometrial cancer cells." (PMID 21062439, 2010). "IDO1 may act as an immunomodulatory factor that contributes to the endometrial cancer microenvironment, and endometrial cancer cells have greater IDO1 activity than noncancerous endometrial cells, emphasizing the importance of determining IDO1 activity in cancerous tissues." (PMID 41282989, 2025). "ERV3-2 expression was correlated with all three genes in ER− HER2− and HER2+ breast, colon, and endometrial cancers; and IDO-1 and IDO-2 (but not TDO-2) in ER+ HER2− breast, gastric, lung, prostate, cervical, and head-neck squamous cell cancers." (PMID 34367262, 2021). "Exceptionally, IDO1-expressing tumor cells were often found in the absence of any inflammation in endometrial carcinomas." (PMID 26895379, 2016).
Arthritis (34 papers, 2014 to 2025). Inflammation of a joint. "When ApoE deficiency is combined with the deletion or inhibition of IDO1, however, there is a marked exacerbation of the pathology in arthritis, with the deposition of atherosclerotic plaques comparable to the natural disorder in humans." (PMID 32194572, 2020). "Patients carrying any of these three coding IDO1 gene variants were more likely to show extraintestinal manifestations such as arthritis, uveitis, and perianal disease, indicators of CD severity." (PMID 31781097, 2019). "The finding that IBD associated arthritis and uveitis occurred in patients with IDO1 SNPs is supported by studies linking elevated IDO1 expression to disease activity and pathogenesis in both inflammatory arthritis and experimental uveitis." (PMID 25541686, 2014). "To validate the multivariate comparisons, we performed univariate analysis and found extraintestinal disease manifestations (EIM) including IBD-associated arthritis and uveitis were more common in IDO1 SNP patients (OR 9.89, CI 2.0–49.4 with P = 0.005 and FDR = 0.019)." (PMID 25541686, 2014). "This is consistent with evidence that IDO1 inhibition or deletion exacerbates arthritis, while kynurenine reduces its severity." (PMID 36389710, 2022). "The differing roles of IDO1 and IDO2 in these different model systems of arthritis underscore the importance of using genetic knockouts or specific inhibitors of the individual IDO enzymes to properly assess IDO1 and IDO2 function." (PMID 35493480, 2022). "We and others have identified DCs as the main immune cell population expressing IDO1 in many pathological conditions such as cancer, leukemia, arthritis, and viral and bacterial infections." (PMID 36227694, 2022). "Some reports concluded that the blocking of IDO1 increased the inflammatory responses in the arthritis animal model." (PMID 34956209, 2021). "Previous studies reported that the inhibition of IDO1 can increase inflammation through Th1, Th17, or B lymphocytes, which are expected to enhance arthritis, but the effect of IDO1 inhibition on the cartilage and chondrogenesis remains to be explored." (PMID 34956209, 2021). "Overall, IDO1 seems to have a clear protective role in experimental models of arthritis and, at least in a subgroup, in RA patients." (PMID 32899743, 2020). "In other studies, IDO1 upregulation in RA was found to be responsible for the decrease in the serotonin/Trp ratio in the hippocampus of mice suffering from arthritis." (PMID 32899743, 2020). "In the case of RA, we have demonstrated that the inhibition of IDO (by 1-methyl-DL-tryptophan) or deletion of IDO1 increased the severity of arthritic symptoms in the collagen-induced model of arthritis (CIA)." (PMID 32194572, 2020). "The genetically impaired IDO1 activation thus reproduced the effect of arthritis exacerbation in IDO1–/– mice." (PMID 32194572, 2020). "In fact, sCD83 administration resulted in a long-term and antigen-specific immunomodulation in arthritis by upregulating IDO1 and TGF-β, reducing auto-aggressive effector T cells, inducing Treg cells, and promoting a direct impairment of osteoclastogenesis." (PMID 32899743, 2020). "Using the dko mice together with the KRN model of arthritis, we demonstrate that IDO2 mediates the autoreactive B cell response driving arthritis through an IDO1-independent mechanism." (PMID 32973768, 2020). "In general, a greater number of studies in experimental models of arthritis was performed for Trp, as compared to Arg metabolism, and indicated that at least the IDO1-mediated kynurenine pathway clearly exerts protective effects." (PMID 32899743, 2020). "Here, we find that autoantibody levels and arthritis were also reduced in IDO1/IDO2 dko mice, confirming that IDO2 mediates autoreactive B cell responses in an IDO1-independent manner." (PMID 32973768, 2020). "Conversely, administration of the IDO1 product kynurenine or synthetic analogs of tryptophan catabolites ameliorates arthritis." (PMID 27036118, 2016).
Arthritis (continued). "In the KRN model of spontaneous RA, we found that IDO2 was crucial for the development of arthritis but that IDO1 was completely dispensable." (PMID 25477879, 2014). "Studies of kynurenine supplementation, or inhibition of kynurenine production with the IDO1 inhibitor 1-methyl-tryptophan (1-MT) have shown conflicting effects on arthritis severity: 1-MT treatment ameliorates disease in the K/BxN murine model but exacerbates disease in the CIA model." (PMID 38113112, 2023). "But other clinical studies suggested that the overexpression of IDO1 could play a role in the stiffness of joints and may increase the severity of arthritis." (PMID 34956209, 2021). "The activity of IDO1 contributes to tryptophan catabolism and the induction of arthritis." (PMID 34956209, 2021). "Dko mice had a reduction in the number of autoantibody secreting cells and severity of arthritis: however, percentages of differentiated T cells and their associated cytokines were not reduced compared to IDO1 ko or wild-type mice." (PMID 32973768, 2020). "This theory is supported by other studies demonstrating that IDO1 deficiency does not affect the inflammation in murine models of arthritis, pregnancy, or bacterial infection." (PMID 32180772, 2020). "However, the reduced arthritis in IDO2 ko mice could be due to alterations in the expression or activity of IDO1 in the mice." (PMID 32973768, 2020). "However, in DC from arthritis patients, circulating DC expressed both IDO1 and IDO2." (PMID 25477879, 2014). "It has been demonstrated that IDO2 knockout inhibits the production of autoantibodies and alleviates symptoms in arthritis models, suggesting that IDO2 acts as a pro-inflammatory mediator directly within B cells, while IDO1 has markedly different functions." (PMID 39880074, 2025). "Like the KRN model, development of arthritis in the CIA model is mediated by autoantibodies, though the specific effect of IDO1 and IDO2 on the B cell compartment remains to be established." (PMID 35493480, 2022). "IDO1 gene expression can be inhibited by DNA methylation at the promoter, and treating mice with experimental arthritis with the DNA methyl-transferase (DNMT) inhibitor decitabine reduced the symptoms of arthritis and prevented the occurrence of relapse, in an IDO-dependent manner." (PMID 37296860, 2023). "This indicates that absence of IDO2 alone, independent of the presence or absence of IDO1 expression, was responsible for the reduced autoreactive B cell response and alleviation of arthritis in the IDO2 ko mice." (PMID 32973768, 2020). "Studies have demonstrated that IDO2 but not IDO1 is required for activation of CD4+ T cells, autoantibody production, and development of disease in a mouse model of arthritis." (PMID 35020864, 2022). "Confirming that this effect wasn’t due to alterations in the expression of IDO1 following deletion of IDO2, double knockout mice lacking both IDO1 and IDO2 show the same reduction in arthritis as is seen in IDO2 knockouts alone." (PMID 35493480, 2022).